SPP1 (secreted phosphoprotein 1)
Diseases named in the same sentence as SPP1 in open-access papers (continued):
Sharing a sentence is not in itself a finding about the gene and the disease.
cancer (continued). "MIF and SPP1 play critical roles in various diseases, including cancer, and present promising therapeutic targets." (PMID 38191424, 2024). "Initially, employing single-cell sequencing, we analyze multiple malignant cell subpopulations and cancer-associated fibroblast (CAF) subpopulations, revealing their interplay through receptor-ligand interactions, with a particular focus on SPP1." (PMID 39749197, 2024). "Despite an overall suppression of macrophage-related pathways, the activities of SPP1 and MIF remained more vigorous, potentially indicating a closer association of these pathways with cancer progression." (PMID 39850883, 2024). "An extensive analysis including various cancer types revealed that half of all cancers displayed SPP1-expressing clusters of macrophages and that SPP1 + Macs were associated with a worse prognosis." (PMID 39726047, 2024). "Recent studies have indicated that SPP1 + macrophages (SPP1 + Macs) constitute a common TAM cluster in various cancer types and that SPP1 is a marker of Inflam-TAMs and proangiogenic TAMs (Angio-TAMs)." (PMID 39726047, 2024). "The role of SPP1 in cancer thus appears to vary according to cancer subtype, suggesting the need for further research tailored to specific cancer types to explore its clinical implications." (PMID 39409192, 2024). "Higher CXCL9 and lower SPP1 expression was recently found to be correlated with a macrophage prognostic score in cancer patients." (PMID 38187708, 2024). "SPP1 + macrophages also showed higher expression of SIRPA expression levels compared to SPP1- macrophages across six cancer types, which was verified by subsequent mIHC assays." (PMID 39696410, 2024). "A recent pan-cancer analysis using public data from TCGA showed that SPP1 is overexpressed in most cancers." (PMID 39149248, 2024). "Consistent with this, pan-cancer analysis has pinpointed SPP1+ TAMs as the most pro-tumorigenic macrophage subset across various cancers." (PMID 39030280, 2024). "In summary, this study builds upon previous reports highlighting the significant role of SPP1 in cancer pathogenesis." (PMID 39727934, 2024). "SPP1, a multifunctional secreted phosphorylated glycoprotein, is known for its involvement in cancer cell growth and resistance to chemoradiotherapy, inducing EMT, autophagy, aberrant glucose metabolism, epigenetic alterations, and reduction of drug uptake." (PMID 38521868, 2024). "Due to its involvement in diverse biological processes, SPP1 has been recognized as a significant contributor to numerous cancer types." (PMID 38329443, 2024). "The most dominant subcluster was characterized by expression of “secreted phosphoprotein 1 (Spp1)+” (26.8–34.2% of total cancer cells)." (PMID 38802348, 2024). "With reference to myeloid cells and consistent with previous reports 26, 27, we identified LGMN+ and SPP1+ TAM clusters in our data, with a particular association with cancer cells." (PMID 38169544, 2024). "Studies also show that SPP1 is overexpressed in various malignant tumor, including breast cancer, gastric cancer, lung cancer." (PMID 38956502, 2024). "In the presence of IgG, cancer cell CM with progranulin induced the expression of myMAF genes, including Spp1, Acta2, and Postn, while the neutralisation of LIF partially suppressed this induction." (PMID 38678021, 2024). "Signaling molecules such as MIF and SPP1 are predominantly delivered by the C2-E.T cluster and represent main the pro-cancer signals between cells in the early stages of tumorigenesis." (PMID 38191424, 2024). "Since SPP1+ macrophages were shown to be important for the TME in previous studies, we further analyzed the SPP1 pathway in macrophages and analyzed SPP1+ macrophages in pan-cancer." (PMID 38648200, 2024). "Among these, two of the majors signaling molecules, MIF and SPP1, were mainly secreted by a subpopulation of cancer stem cells." (PMID 38191424, 2024).
cancer (continued). "We also identified relationships between SPP1 and the expression of 28 TILs in human cancers, with significant correlations with 23 of these immune cells." (PMID 38329443, 2024). "Another study by our team evaluated NETs enrichment levels based on 23 NETs-related genes in 22 cancers and reported that the combination of SPP1 upregulation and NETs enrichment was closely related to EMT in cancers." (PMID 39529085, 2024). "It is noteworthy that previous pan-cancer studies have demonstrated a ubiquitous co-expression of SPP1 and angiogenesis features within TAMs, contributing to angiogenesis." (PMID 39232806, 2024). "SPP1 has been suggested as a potential target for evaluating prognosis and immunotherapy in multiple human cancers." (PMID 39409192, 2024). "Across all donors, MIF and SPP1 signalling was prominent in cancer cells while SPP1 signalling was also active in M2 macrophages." (PMID 39149248, 2024). "The multifaceted role of SPP1 in the intricate landscape of cancer progression, neurobiology, and aging-related neurodegenerative conditions underscores its diverse and impactful contributions to physiological processes across different biological contexts." (PMID 38248779, 2024). "The role of the SPP1 signaling pathway is crucial in cancer, involving cell adhesion, mobility, immune response, and inflammation." (PMID 39850883, 2024). "Based on the distribution of prognostic marker genes in the ten cell clusters, SPP1 was primarily found in monocytes, DCs and malignant tumor cells." (PMID 37346073, 2023). "As SPP1 expression in TAMs is induced by GM-CSF, and GM-CSF is produced by cancer cells stimulated with anti-cancer agents, cell-to-cell communication via GM-CSF and SPP1 is thought to be involved in the development of chemoresistance." (PMID 37190178, 2023). "Based on Cellchat analysis, we found that Spp1 signaling was initiated by cancer cells in networking with other cells in the TME." (PMID 37699010, 2023). "We further selected two representative genes, SPP1 and MCM2 to study the mutation and copy number variation profiles at the pan-cancer level." (PMID 37723560, 2023). "SPP1+ TAMs were described in 8 cancer subtypes: BC, PCA, Lung, CRC, Uterine corpus endometrial, Nasopharyngeal, Ovarian and Thyroid carcinoma, preferentially expressing an angiogenic signature." (PMID 37342322, 2023). "Biologically, SPP1 was reported to play a cancer-promoting role by regulating cell proliferation, motility, invasion and angiogenesis." (PMID 38067407, 2023). "SPP1 has been reported to be a key gene in many cancers and can divide patients into subgroups with different immune cell infiltration or different prognoses." (PMID 38111044, 2023). "The data indicated that the SPP1 gene was altered in 2.19% of 411 bladder cases which were found to harbor the highest proportion of SPP1 gene amplifications with 1.22% relative to other cancer types." (PMID 38067407, 2023). "HLA-G+ cancer cells can induce macrophages to polarize towards an M2 phenotype, characterized by the expression of SPP1 (osteopontin)." (PMID 38187388, 2023). "Similar to the potential cross-talk between mesothelial cells and cancer cells, we identified possible interactions between LA-TAMs/mesothelial cells by SPP1, RETN, LGALS9, NAMPT, and HBEGF secretion." (PMID 37649596, 2023). "In a word, high expression of SPP1 in TAMs is related to poor prognoses and immunosuppression in cancers." (PMID 37187751, 2023). "As with circulating SPP1, high expression of SPP1 on cancer cells is correlated with poor prognosis." (PMID 37190178, 2023). "SPP1 is well known to be involved in cancer cell growth and resistance to chemoradiotherapy through the induction of epithelial–mesenchymal transition (EMT), autophagy, aberrant glucose metabolism, epigenetic alterations, and reduction of drug uptake." (PMID 37190178, 2023). "The results of the TIMER website analysis showed that SPP1 was highly expressed in almost all cancers." (PMID 36688087, 2023).
cancer (continued). "A candidate for this use is the metastasis mediator Osteopontin (OPN, secreted phosphoprotein 1, SPP1, gene ID 6696), which is over-expressed in about 30 malignancies." (PMID 37095438, 2023). "Recent studies have depicted SPP1 as a prominent marker for TAMs with M2‐like immune‐suppressive functions and poor prognosis in various cancers." (PMID 38115703, 2023). "A clear association of CD44, PTGER4, and α4β1 in SN macrophages, plasma cells, cancer cells, and T cells was observed with upregulated SPP1 in macrophages." (PMID 37745301, 2023). "SPP1 signaling pathway, which was reported to regulate cancer cell proliferation and migration was also up-regulated." (PMID 37022488, 2023). "Other ligand‒receptor pairs involved interactions between cancer cells and SPP1+ TAMs through PGRMC2-CCL4L2 and interactions between CAFs and TAMs through CXCL12-CXCR4." (PMID 36596773, 2023). "The cellular functions of SPP1 have also been investigated in cancer and other disorders including obesity, diabetes and cardiovascular disease." (PMID 38067407, 2023). "Prior studies suggest that polarization of macrophages toward an SPP1+ state is a result of TME properties, including oxygen tension, the presence of FAP+ cancer-associated fibroblasts, and ECM composition, consistent with our pathway analysis." (PMID 38036590, 2023). "Specifically, we revealed that SPP1 was a potential prognostic and immunotherapy biomarker in multiple human cancers using pan-cancer analysis." (PMID 37097499, 2023). "SPP1-induced autophagy played a critical role for stem-like properties and chemo-resistance of cancer cells by activating the PI3K/mTOR pathway." (PMID 37190178, 2023). "The results indicated that SPP1 is a cancer promoter (oncogene), while PECAM1 and PIK3R1 are cancer suppressor genes." (PMID 36688087, 2023). "Osteopontin (OPN), also called secreted phosphoprotein 1 (SPP1) is a matricellular glycoprotein whose expression is elevated in various types of cancer and which has been shown to be involved in tumorigenesis and metastasis in many malignancies." (PMID 37318593, 2023). "Recent studies utilizing spatial transcriptomics and single-cell sequencing have shed light on the interaction between HLA-G+ cancer cells and SPP1+ macrophages in the immune microenvironment at the invasive front of CRC." (PMID 38187388, 2023). "The expression of SPP1 is significantly increased and related to poor prognosis in multiple cancer types, while decreasing SPP1 expression inhibits the proliferation, migration and invasion of cancers." (PMID 37097499, 2023). "So, we further analyzed the methylation levels of these genes in pan-cancer, and we found that most of them, such as SPP1, RHBDF1, and NSMCE2, were significantly demethylated, which was consistent with the high expression of these genes specifically in tumors." (PMID 37723560, 2023). "Taken together, the current study complements the previous reports on the major role of SPP1 in cancer pathogenesis." (PMID 38067407, 2023). "LA-TAMs also participated in the modification of cancer cells by SPP1, VEGFA, RETN, GRN, ADGRE5, and HBEGF secretion." (PMID 37649596, 2023). "A genome-wide association of a European CKD population revealed two replicated loci, one upstream of SPP1, and another mapping onto KLKB1 encoding pre-kallikrein, which is involved in blood pressure control, inflammation, cancer, and cardiovascular disease." (PMID 37239027, 2023). "We initially looked at the gene expression profile of SPP1 mRNA levels across a panel of multiple primary cancers and their matching normal tissues (24 in total) using the TCGA database." (PMID 38067407, 2023). "Conversely, the ability of SPP1+ macrophages to influence carcinoma cell identity appeared to correlate with expression levels of CD44, the Osteopontin receptor." (PMID 38036590, 2023).
cancer (continued). "Secretory phosphorylated protein 1 (SPP1) is a secreted multifunctional phosphorylated protein that specifically binds and activates matrix metalloproteinases (MMPs) in cancer." (PMID 36225568, 2022). "Our findings suggested that SPP1 is a potential target for evaluating patient prognosis and immunotherapy in multiple human cancers." (PMID 35067176, 2022). "We assessed the genetic alterations of the SPP1 genes in patients with cancer using the cBioPortal database." (PMID 35067176, 2022). "The Transwell assay illustrated that knockdown of CD44 or SPP1 notably prevented cancer cell migration." (PMID 35790930, 2022). "The Oncomine database showed that the expression of SPP1 significantly higher in cancer samples than normal tissues in most datasets." (PMID 36585688, 2022). "Studies have reported that the expression level of SPP1 is closely related to the occurrence, development, invasion, and metastasis of malignant tumors." (PMID 35154316, 2022). "Spp1/osteopontin has been shown to promote survival of other cell types including peripheral immune cells and cancer cells." (PMID 35481836, 2022). "We found genes related to extracellular matrix organization, such as SPP1, MT1L, and COL3A1 (among others), which functioned as NET-associated regulatory genes exclusively in cancer types with poor NET-related survival." (PMID 35432310, 2022). "Some BIIGs were upregulated in multiple cancer types: Top2a, Mki67, Rrm2, Mcm6, and Spp1 were upregulated in more than eight cancer types, while Emp1, Ptx3, and Socs3 were upregulated in seven cancer types." (PMID 36605216, 2022). "Our study reveals a strong positive correlation between SPP1 and NETs in multiple cancer types, and co-upregulation of SPP1 expression and NET score were related to higher EMT scores in all examined cancer types." (PMID 35432310, 2022). "For example, we found that the TME induced the transformation of CXCL11+ macrophages with the manifestation of M1-like macrophages into SPP1+ macrophages with a higher M2 signature, promoting cancer progression." (PMID 36357424, 2022). "Increased CD44 and PTGER4 in many cell types such as macrophages, DCs, cancer cells, and T cells were correlated to upregulated SPP1 in macrophages; the activated interaction pairs were correlated to cancer immune escape and metastasis." (PMID 35874770, 2022). "Immunohistochemical results revealed that these S100P + SPP1 + cells were mostly present in the invasive regions of cancer nodules in certain iCCAphl cases." (PMID 35347134, 2022). "The Human Cancer Metastasis Database analysis showed that SPP1 expression levels were significantly higher in bone metastases than in lymph node and posterior peritoneum metastases, thus correlating the expression of SPP1 with the progression of mCRPC." (PMID 36176747, 2022). "Previous studies showed that SPP1 participate immune and inflammatory response, and it can further promote cancer invasiveness in inflammatory conditions." (PMID 36585688, 2022). "SPP1, as an important gene in certain cancer types, involved in the occurrence and development of tumors." (PMID 35067176, 2022). "Cancer-specific survival (CSS) was significantly shorter in the group with high scores for SPP1 on TAMs." (PMID 36139536, 2022). "In this study, we analyzed the expression and prognosis of SPP1 in 33 different types of cancers by three different online databases: Oncomine database, GEPIA database and TIMER database." (PMID 36585688, 2022). "In the present study, we aimed to explore the SPP1 expression profiles and oncogenic features among human cancers using the TCGA project for comprehensive analysis." (PMID 35067176, 2022). "The macrophage chemotactic protein SPP1 is highly expressed in infiltrating macrophages after tissue injuries, can sustain cancer cell survival, and promote angiogenesis." (PMID 35874770, 2022).
cancer (continued). "The results revealed that the expression levels of SPP1 were significantly increased in cancerous tissues compared with normal tissues in a variety of cancer types, including GC." (PMID 36612160, 2022). "Subsequently, the SPP1 expression level in various cells, including macrophages and cancer cell lines, was examined by qRT-PCR." (PMID 36139536, 2022). "In the present study, we analyzed the expression of SPP1 in multiple tumors using the Oncomine and TCGA databases, revealing significantly differences of SPP1 expression in various types of cancer." (PMID 35067176, 2022). "SPP1 expression was observed to correlated positively with immune checkpoint gene expression in multiple types of cancer." (PMID 35067176, 2022). "Osteopontin, also called secreted phosphoprotein 1 (SPP1), is expressed by cancer cells and is known as a poor prognostic factor." (PMID 36139536, 2022). "We revealed that the macrophage-derived SPP1 suppresses the apoptosis of cancer cells under the administration of anticancer drugs." (PMID 36139536, 2022). "In pancreatic cancer, CAFs can secret OPN/SPP1 to regulate the CD44 axis in cancer cells enhancing cancer stemness." (PMID 36319622, 2022). "We used data from XENA-TCGA_GTEx to investigate SPP1 expression profiles between cancerous and normal tissues in different cancer types." (PMID 36612160, 2022). "As expected, almost all cancer types showed significantly higher EMT scores in the NETs/SPP1-high group." (PMID 35432310, 2022). "The results showed that SPP1 expression was closely related to the advanced stage of cancer and poor prognosis of patients with advanced GC." (PMID 36612160, 2022). "SPP1 is expressed in most human tissues, including the brain, vascular tissue, kidney, and liver, and has been reported to regulate cancer cell proliferation through the activation of the MAPK pathway." (PMID 35572724, 2022). "Aberrant expression of secreted phosphoprotein 1 (SPP1) protein has been observed in several cancers." (PMID 36038839, 2022). "According to this spatial transcriptomics analysis, we identified significant SPP1 expression in OGCs together with cancer cells." (PMID 36148946, 2022). "In order to explore the SPP1 expression levels in different cancers and the corresponding normal tissues, three different online databases were included in our study." (PMID 36585688, 2022). "SPP1 expression was observed to correlated positively with immune checkpoint genes in multiple types of cancer." (PMID 35067176, 2022). "We compared the gene expression levels between the two cancer groups and defined a set of genes universally related to NETs, among which SPP1 was highly expressed in cancers with poor NET-related survival (fold change of 2.3)." (PMID 35432310, 2022). "SPP1, also known as Osteopontin (OPN), promotes cancer progression and metastasis through activation of NFkB signaling, which regulates extracellular matrix interactions." (PMID 36180422, 2022). "Increased and decreased SPP1 expression had different prognostic values depending on the type of cancer." (PMID 35067176, 2022). "In our present study, we comprehensively assessed SPP1 expression and its correlation with prognostic value of cancer patients in databases including Oncomine, GEPIA, TIMER, PrognoScan, HPA and Kaplan–Meier plotter." (PMID 36585688, 2022). "Our computational results and previous studies suggested that SPP1 was highly expressed in numerous cancers and its expression level correlates with the metastatic level of several tumors." (PMID 34721759, 2021).